TNF (tumor necrosis factor)
Diseases named in the same sentence as TNF in open-access papers (continued):
Sharing a sentence is not in itself a finding about the gene and the disease.
vitiligo (continued). "In vitro, direct analysis of skin T cells from margins of vitiliginous skin show that polarized type-1 T cells (CD4+ and particularly CD8+), which predominantly secrete interferon (IFN)-γ and TNF-α are associated with the destruction of melanocytes during active vitiligo." (PMID 23284977, 2012). "Thus, it becomes pertinent to study all TNF-α promoter polymorphisms in adequate number of vitiligo patients and controls to elucidate the role of these polymorphisms in vitiligo susceptibility and to analyze the possible genotype - phenotype correlation." (PMID 23284977, 2012). "to determine whether the promoter polymorphisms of TNF-α [−238 (G/A; rs361525), −308 (G/A; rs1800629), −857 (C/T; rs1799724), −863 (C/A; rs1800630) and −1031 (T/C; rs1799964)] are associated with vitiligo susceptibility and modulate TNF-α transcript and protein levels." (PMID 23284977, 2012). "These aldehydes also activate immune responses by functioning as DAMPs, stimulating dendritic cells and inducing pro-inflammatory cytokines such as IL-6, IL-1β, and TNF-α, contributing to vitiligo’s autoimmune component." (PMID 40427437, 2025). "Paradoxically, cases of new-onset vitiligo or worsening of existing vitiligo have also been reported during anti-TNF therapy." (PMID 40861456, 2025). "TNF-α appears to be a key factor in the pathogenesis of vitiligo, as it inhibits melanocyte proliferation and function." (PMID 40861456, 2025). "Our cell–cell communication analysis further supports this model, revealing Mac‐InflamAP as a central signaling hub in vitiligo skin, engaged in bidirectional activation loops with T cells and in TNF‐driven MEL suppression." (PMID 41498037, 2025). "And studies have suggested that some proinflammatory cytokines that are generally higher in vitiligo patients, such as tumor necrosis factor (TNF)-α, interleukin (IL)-1 and IL-6, are also involved in the development of atherosclerosis." (PMID 40169829, 2025). "Activated CD8+ T cells release IFN-γ and TNF-α, inducing local chemotaxis mediated by the CXCL10-CXCR3 axis, causing apoptosis and clearance of melanocytes, manifested as vitiligo-like depigmentation." (PMID 40861456, 2025). "This study further demonstrates the significant upregulation of miRNA-146a and proinflammatory mediators (NF-κB, IL-6, and TNF-α), accompanied by the downregulation of Foxp3 in vitiligo tissues." (PMID 40723924, 2025). "Most notably, Mac‐InflamAP demonstrated significantly increased TNF signaling to MELs in vitiligo, which is consistent with the known cytotoxic effects of TNF‐α on pigment‐producing cells." (PMID 41498037, 2025). "PRP has been shown to suppress the expression of key proinflammatory cytokines, including interleukin-1 (IL-1), interferon-gamma (IFN-γ), and tumor necrosis factor-alpha (TNF-α), all of which are critically involved in the pathogenesis of vitiligo." (PMID 41226837, 2025). "The elevated levels of proinflammatory cytokines, particularly TNF-α and IL-6, in the current study patients support previous reports linking these mediators to vitiligo pathogenesis and activity." (PMID 40723924, 2025). "In many studies, vitiligo patients demonstrated higher mean serum TNF-α levels than controls, with the level being correlated with disease activity." (PMID 39201060, 2024). "The serum of monobenzone-induced vitiligo mice exhibited a marked increase in proinflammatory cytokines, such as TNF-α, IFN-γ, and IL-6." (PMID 38542385, 2024). "In fact, unexpected worsening of a pre-existing vitiligo and de novo development of vitiligo lesions were observed in a minority of patients treated with anti-TNF-α agents due to other autoimmune disorders, discouraging the popularity of this strategy." (PMID 39063004, 2024). "These activated T cells produce pro‐inflammatory cytokines such as IFN‐γ and TNF‐α, which further drive inflammation and melanocyte damage in vitiligo." (PMID 39313936, 2024).
vitiligo (continued). "To further investigate the anti-inflammatory ability of FHB on vitiligo mice at the transcriptional level, we used PCR to detect the expression of IL-6 and TNF-α in the lesioned skin." (PMID 37575231, 2023). "The FHB therapy group significantly reduced the levels of inflammatory factors TNF-α and IL-6 in the blood of vitiligo mice, which was consistent with the results anticipated by network pharmacology." (PMID 37575231, 2023). "The existing data on the potential correlation between vitiligo and anti-TNF-α agents remain inconclusive due to limited evidence." (PMID 38139134, 2023). "These include a decrease in IL-17, 23, alfa-TNF and gamma-interferon while increasing IL-10, overall decreasing proinflammatory cytokines (which are increased in vitiligo-affected skin) and increasing suppressive cytokines." (PMID 38139134, 2023). "Alghamdi’s group investigated the efficacy and safety of anti-TNFα agents in six vitiligo patients (two patients treated with infliximab, two with adalimumab, and two with etanercept)." (PMID 38068541, 2023). "Larger-scale and long-term studies are warranted to comprehensively assess the efficacy of anti-TNF-α agents in vitiligo treatment." (PMID 38139134, 2023). "IL-33 inhibits melanocyte growth in vitiligo, blocking growth factors and increasing the release of pro-inflammatory cytokines IL-6 and TNFα." (PMID 37275386, 2023). "IL-1β, HMGB1, IL-8, and IL-6 TNF-α are believed to have a crucial role in the innate immune response, and their levels were considerably increased in vitiligo patients' serum and skin." (PMID 36920542, 2023). "Cytokines (e.g., TNF-α and IL-6) -mediated inflammation is important in the development of vitiligo, and CHE and TYR are molecules related to melanin synthesis." (PMID 37575231, 2023). "On the other hand, Kim’s group observed improvement in refractory vitiligo in two patients treated with the anti-TNFα agent etanercept." (PMID 38068541, 2023). "In comparison to the control group, HQ-induced vitiligo mice had a significant increase of IL-6 and TNF-α in both skin tissues and melanocytes, but FHB therapy can effectively decrease them." (PMID 37575231, 2023). "A vitiligo paradoxical adverse reaction following TNF-α agents has been documented during psoriasis treatment." (PMID 38139134, 2023). "The effect of TNF-α on cultured human skin melanocytes plays important role in vitiligo through NF-κB activation." (PMID 34839983, 2022). "One study showed that IL15 causes the expression of NKG2D in memory CD8 + T Cells in skin with vitiligo, triggering the production of IFNγ and TNFα." (PMID 35643735, 2022). "ROS production is also increased by TNF-α, further promoting stress signals in vitiligo melanocytes." (PMID 33717132, 2021). "In patients with vitiligo, PBMCs can secrete proinflammatory cytokines such as IL-1β, IL-6, IL-8, and tumor necrosis factor (TNF)-a, and infiltrate around the lesions of vitiligo, suggesting that PBMCs play important roles in the pathogenesis of vitiligo." (PMID 34941177, 2021). "While its role as an apoptotic mediator has been shown in multiple cell types, in vitiligo, TNF-α inhibits melanogenesis by activating the transcription factor NF-κB." (PMID 33717132, 2021). "Stopping the offending biologic (e.g., anti-TNF-α therapy) should be weighed against the severity of the vitiligo or alopecia areata." (PMID 33802483, 2021). "TRM cells infiltrate vitiligo skin and contribute to the maintenance of disease, producing IFNγ and TNFα and exhibiting cytotoxic activity against melanocytes." (PMID 34768860, 2021). "Interleukin (IL)-1β, IL-6, and tumor necrosis factor alpha (TNF-α) are inflammatory cytokines, which are anti-melanogenic factors and are upregulated in the skin and sera in patients with vitiligo." (PMID 34638746, 2021).
vitiligo (continued). "In fact, anti‐TNF‐α agents have been used in treatment of vitiligo with uncertain results, even if in vivo studies demonstrated that TNF‐α inhibits differentiation of melanocytes from stem cells." (PMID 34436817, 2021). "At the same time, other inflammatory cytokines, such as TNFα and INFγ, increase in response to cellular damage and are involved in the progression of vitiligo." (PMID 34768860, 2021). "This is associated with higher melanocyte apoptosis and production of pro-inflammatory cytokines IL-6 and TNF-α in vitiligo." (PMID 33717132, 2021). "Some clinical trials, that have used anti-TNF-α agents for the treatment of vitiligo, have reported a gradual improvement of illness that signified the involvement of TNF-α in vitiligo pathogenesis." (PMID 33370782, 2020). "In vitiligo, TNF-α plays a role in the development cytotoxic T cells (CTLs) and enhances expression of IFN-γ, which are implicated in imitation of vitiligo development." (PMID 33335528, 2020). "Cytokines have remarkable roles in the pathogenesis of vitiligo, such as IL-1, IL-6, and TNF-α; interleukin 27 (IL-27) is a new member of the IL-6/IL-12 family, mainly released by activated antigen-presenting cells." (PMID 32616337, 2020). "This study aimed to detect the serum TNF-α (sTNF) level (by ELISA) and the rs1800629 (by real-time PCR) among AA and vitiligo Egyptian patients and to determine their relation with disease duration and severity." (PMID 33370782, 2020). "This study has demonstrated the considerable role of TNF-α promoter polymorphisms on the sTNF-α as we reported a significant rise in the sTNF-α level with the mutant genotypes (G/A and A/A) in comparison to the normal G/G genotype which might be playing a central role in vitiligo pathogenesis." (PMID 33370782, 2020). "Differences in TNF-α serum level according to the difference in genotypes among alopecia areata and vitiligo patients." (PMID 33370782, 2020). "While in vitiligo patients, those with TNF-α-308 G/G genotypes exhibited significantly lower sTNF-α levels than those with G/A genotypes (p<0.0001)." (PMID 33370782, 2020). "As seen in alopecia areata and vitiligo, numerous studies documented increased TNF-α and IL-17 levels while the inhibition of both cytokines failed in these disorders." (PMID 31440261, 2019). "Overall, repigmentation using TNF-α blockers is limited in vitiligo and this approach was considered to be ineffective." (PMID 31440261, 2019). "Overall, disappointing results of TNF-α blockers in alopecia areata and vitiligo point to the same conclusion although promising results in toxic epidermal necrolysis suggest TNF-α exerts at least some in vivo Th1-related activities." (PMID 31440261, 2019). "Failure of both TNF-α inhibitors and IL-17A-blockers in alopecia areata and vitiligo limits the involvement of these cytokines in the immune-mediated destruction of skin cells." (PMID 31440261, 2019). "Given the role of TNF-α in the Th1 response, it made sense to test TNF-α inhibitors in alopecia areata and vitiligo." (PMID 31440261, 2019). "To check for the possible signs of systemic inflammation, we measured the concentration of inflammation-associated cytokines (TNF-α, IFN-γ, IL-1b, IL-1Ra, IL-2, IL-5, IL-6, CXCL8, CXCL10, G-CSF, and GM-CSF) in the plasma of vitiligo patients." (PMID 30515176, 2018). "The rationale is that TNF-α immunoreactivity has often been detected in oral and cutaneous LP and that enhanced levels of TNF-α production from melanocytes have also been detected in patients with vitiligo." (PMID 26688760, 2015). "An ointment like tacrolimus (that is effective in the treatment of vitiligo) decreases TNF-alpha expression in epidermis and inhibits the activation of the nuclear factor for activated T cells (NFAT)." (PMID 24665368, 2014). "Intriguingly, genetic ablation of TNF-α or perforin had minimal effect on the development of vitiligo." (PMID 24586745, 2014).
vitiligo (continued). "The authors suggested that high vitiligo disease activity score is related to high TNF-alpha level in the epidermis." (PMID 24665368, 2014). "This confirms the previous observations that IL-6 and IL-8 levels are elevated in the sera of vitiligo patients while the TNF-α and IFN-γ levels are decreased, and that IL-6 is highly produced in the vitiligo lesional skin." (PMID 23042234, 2013). "Female patients with vitiligo showed significantly higher TNF-α expression as compared to male patients (p = 0.0073)." (PMID 23284977, 2012). "Analysis of TNF-α levels based on the gender and disease progression suggests that female patients and patients with active vitiligo had higher levels of TNF-α." (PMID 23284977, 2012). "The study revealed significant increase in TNF-α transcript and protein levels in vitiligo patients compared to controls." (PMID 23284977, 2012). "Our results also indicate that active vitiligo patients have significantly higher TNF-α transcript and protein levels as compared to the patients with stable vitiligo which signifies the role of TNF-α in disease progression." (PMID 23284977, 2012). "Active vitiligo patients showed significantly increased expression of TNF-α transcripts as compared to the patients with stable vitiligo (p<0.0001)." (PMID 23284977, 2012). "to measure and compare TNF-α transcript and protein levels in patients with vitiligo and in unaffected controls." (PMID 23284977, 2012). "In vitiligo patients, the TNF-α haplotypes: GATCC, AGTCT, AGCCT and AACCT were found to increase sTNF-α levels (p = 0.031, p = 0.003, p = 0.009 and p = 0.007 respectively) with susceptible alleles (−238A, −308A, −857T and −1031C) as compared to controls." (PMID 23284977, 2012). "The study also emphasizes the influence of TNF-α on the disease progression, onset of the disease and gender biasness for developing vitiligo." (PMID 23284977, 2012). "In particular, haplotypes: AATCC, AACCT, AGTCT, GATCT, GATCC and AGCCT were found to increase the TNF-α levels in vitiligo patients." (PMID 23284977, 2012). "In the present study, we have made an attempt to understand the role of TNF-α in vitiligo pathogenesis." (PMID 23284977, 2012). "Comparison of the findings showed significantly increased expression of TNF-α transcripts in 157 vitiligo patients than in 174 unaffected controls after normalization with GAPDH expression as suggested by mean ΔCp values (p = 0.0005)." (PMID 23284977, 2012). "Interfering with Mfsd4a in melanocytes co-cultured with vitiligo model T cells significantly improved melanocyte activity, inhibited the levels of inflammatory cytokines TNF-α, IL-1β, and IL-6, reduced melanocyte apoptosis, and inhibited JAK/STAT3 pathway activation." (PMID 40707941, 2025). "In patients younger than 40 years, the risk of developing vitiligo was 3.7 times higher in the anti-TNF group compared with the nonexposed group." (PMID 40861456, 2025). "In this context, TNF-α inhibitors were found to halt depigmentation, but while the activity of vitiligo can be controlled with TNF-α inhibition, real-life data do not support a correlation between disease duration prior to anti-TNF-α exposure and treatment efficacy." (PMID 39063004, 2024). "For example, TNF-α 308 G/A polymorphism (rs1800629) can be a susceptibility/risk biomarker for vitiligo, but not for AA, in Egyptian patients." (PMID 38673994, 2024). "Serum and tissue TNF-α levels directly correlate with the vitiligo extent, duration, and activity." (PMID 39063004, 2024). "It is possible they may also be of value against vitiligo as TNF-α blockage may modulate the immune response and potentially inhibit the progression of vitiligo spots." (PMID 39201060, 2024). "Previous studies suggested that blocking the TNF α pathway may have therapeutic potential in treating vitiligo skin lesions." (PMID 39742272, 2024).
vitiligo (continued). "Nevertheless, TNF-α appears also to play a protective role in vitiligo, activating and promoting the paradoxical development of T-reg cells, a subset of regulatory cells that can secrete IL-10, suppress T cell proliferation, and prevent activation of other components of the immune response." (PMID 39063004, 2024). "Following this rationale, anti-TNF treatments have been described for active vitiligo." (PMID 37175894, 2023). "To assess whether LBP influences innate immune responses in the skin of mice with monobenzone-induced vitiligo, we measured IL-8, IL-6, TNF-α, IFN-γ and IL-1β expression by RT-qPCR." (PMID 36655287, 2023). "Abnormal immune responses and changes in cytokine levels observed in vitiligo patients suggest that targeting pro-inflammatory mediators including TNFα and ILs-12, 23, and −17 could be a promising treatment strategy." (PMID 38068541, 2023). "In this setting, the risk of developing vitiligo and AA in patients with AS, CD, or UC treated with anti-TNF therapy compared to those without anti-TNF agents has been evaluated using the Korea National Health Insurance Claims databases." (PMID 37175894, 2023). "Recent data has shown a significantly higher expression of TNF-α in vitiligo skin." (PMID 36119071, 2022). "In addition, cytokine, including HSP70i, IL-15, IL-17/23, TNF as well as wnt signaling pathway, Tregs, miRNAs have also been proved to be involved in the pathogenesis of vitiligo." (PMID 36119071, 2022). "The mechanism responsible for the TNF-α inhibitors-induced vitiligo is not fully understood." (PMID 36119071, 2022). "In addition, increased levels of innate immunity cytokines including interleukin (IL)-1α, IL-1β, IL-6, IL-8, IL-12, IL-15 and tumor necrosis factor (TNF)-α have been detected in the sera of patients with vitiligo." (PMID 35884944, 2022). "As an anti-inflammatory mediator, TNF-α is considered to play a role in vitiligo, which may promote apoptosis in melanocytes, induce B-cell activation, increase autoantibody production, and inhibit melanogenesis." (PMID 36119071, 2022). "Some cytokines such as KLRG1+ lymphocytes secrete cytotoxic molecules (granzyme B and perforin), inflammatory cytokines (IFN-γ and TNF-α), and inflammatory chemokine receptors (CCR5 and CX3CR1) are involved in gene expression, which are associated with vitiligo." (PMID 33679890, 2021). "Interestingly, keratinocytes in vitiligo lesions aberrantly produce IL-1, IL-6, and TNF-α, which inhibit melanocyte function and elicit an inflammatory response." (PMID 33717132, 2021). "Besides the Th1 response and subsequent TNF-α and IFN-γ production, Th17 cells and L-17A have recently been implicated in the pathogenesis of vitiligo." (PMID 33968147, 2021). "TNF‐α is supposed to be as potential cytokine involved in the vitiligo pathogenesis." (PMID 34436817, 2021). "One case of TNFα induced vitiligo, resolved after ixekizumab therapy, has recently been described." (PMID 34436817, 2021). "In fact, this herbal derivate may induce reduction in TNF-α and IL-6, both of which are increased in vitiligo patients and known inhibitors of human melanocyte proliferation and melanogenesis." (PMID 34356320, 2021). "CD4 and CD8 T cells mainly produce IFN-γ and TNF-α in vitiligo." (PMID 34107850, 2021). "Thus, TNF-α can potentially be both destructive and protective in vitiligo, by promoting CTLs and stimulating Tregs, respectively." (PMID 33335528, 2020). "The results suggest that serum TNF-α levels are significantly associated with the clinical characteristics of AA patients, though not with those of vitiligo patients." (PMID 33370782, 2020). "Relation between TNF-α-308- G/A and clinical characteristics in vitiligo patients." (PMID 33370782, 2020). "A previous study had suggested that melanocyte death in vitiligo patients could be initiated by the increased TNF-α levels." (PMID 33370782, 2020). "This leaves anti-TNF-α treatment option for vitiligo until side effects are fully averted." (PMID 33335528, 2020).